IL10 (interleukin 10)
Diseases named in the same sentence as IL10 in open-access papers (continued):
Sharing a sentence is not in itself a finding about the gene and the disease.
psoriasis (continued). "Earlier studies documented the low-level expression of IL-10 in psoriasis and its reversal after the conventional anti-psoriatic therapies." (PMID 38444844, 2024). "In mouse models, IL10+ Bregs reduced inflammation in several pathologies, including cutaneous hypersensitivity, scleroderma, and psoriasis-like inflammation." (PMID 38203754, 2024). "IL-10, an anti-inflammatory cytokine produced by regulatory T cells, reported as a significant mediator in psoriasis, proved to be an essential inhibitor for pro-inflammatory T cell responses and keratinocyte inflammatory markers." (PMID 38793117, 2024). "Patients with psoriasis have lower levels of IL10+ B cells in their bloodstream, which is consistent with studies in mice showing the crucial role of these cells in suppressing psoriasiform inflammation." (PMID 38203754, 2024). "In a psoriasis mouse model, cutaneous application of sodium butyrate increased IL-10 and FOXP3 expression in T cells and reduced inflammation." (PMID 37953417, 2024). "A significant elevation of these cells seems to be controlled by NFATc1, a transcription factor that controls the activity of IL‐10 production in psoriasis‐like skin inflammation." (PMID 39261978, 2024). "Patients with psoriasis and other cutaneous inflammatory diseases have reduced numbers of circulating IL10+ Bregs during active disease." (PMID 38203754, 2024). "CitLL37, but not native LL37, induced IFN-γ-production by T cells and B cells from psoriasis patients, as well as IL-10-production by the patients’ CD4+ T cells." (PMID 38173716, 2023). "T regs in psoriasis patients have been reported to have reduced suppressive activity that normalizes with sodium butyrate administration and IL-10 levels and expression of Foxp3, IL-17, and IL-6 in psoriatic skin lesions." (PMID 37623895, 2023). "The anti-inflammatory genetic mediators associated with psoriasis are IL1RN, IL4, IL10, IL13, and IL19." (PMID 37569685, 2023). "In this study, the serum concentrations of IL-10 in the psoriasis group were decreased compared to the healthy group, and the IL-10 concentrations negatively correlated with NLR, ESR, CRP, and PASI." (PMID 37596509, 2023). "Medium-term topical application of IMQ to IL-10-knockout (IL-10−/−) mice promotes psoriasis-like skin inflammation." (PMID 37717073, 2023). "The serum concentrations of IL-10 in peripheral blood were lower in the psoriasis group than in the healthy group (P < 0.001), which decreased in the following order: GPP < EP < PA < PV (P < 0.001)." (PMID 37596509, 2023). "Based on the T- and B-cell IFN-γ and IL-10 responses to citLL37 in patients with psoriasis, we identified two distinct clusters of patients: ten high-responders (cluster 1) and nine low-responders (cluster 2)." (PMID 38173716, 2023). "CitLL37 also induced a significant increase in the proportion of IL-10-producing CD4+ T cells from patients with psoriasis compared to unstimulated cultures and cultures stimulated with native LL37, and a similar tendency was observed in the HD group." (PMID 38173716, 2023). "B cells, thought until recently to have a minor role in the pathogenesis of psoriasis, play an important part in the course of psoriasis since regulatory B cells(Bregs) that produce interleukin (IL)-10 seem to ameliorate psoriatic outbreaks." (PMID 37885781, 2023). "Native LL37 induced secretion of IL-10 by MNCs isolated from patients with psoriasis, and a similar trend was observed after stimulation with citLL37." (PMID 38173716, 2023). "CitLL37 induced IL-10-producing CD4+ T cells in patients with psoriasis, exclusively, and IL-10 was detected in the culture supernatants after stimulation of MNCs from patients with psoriasis with LL37 as well as with citLL37." (PMID 38173716, 2023). "For example, HBD-2 can serve as a marker for multiple disease severities, including atopic dermatitis and psoriasis, while IL-10 has been proven to increase together with the severity of orofacial clefts." (PMID 37508659, 2023).
psoriasis (continued). "As a result, the IL-17/IL-10 ratio was increased in the psoriasis group compared to the healthy group, and it positively correlated with NLR, PLR, ESR, CRP, and PASI." (PMID 37596509, 2023). "Recently, B cell-activation plays important roles in different pathological stages of psoriasis, and is correlated with disease severity, whereas the number of IL10-producing regulatory B cells is limited in patients with psoriasis." (PMID 37893484, 2023). "Elevated levels of TNF-α, IL-2, and INF-γ, and reduced levels of IL-10 in psoriasis compared to the control group." (PMID 35454992, 2022). "The diminished level of IL-10 in the serum and skin of patients with psoriasis is critical for the induction of disease flare-ups64,65." (PMID 35869084, 2022). "Among all IL-10 expressing cells in psoriasis skin, 53.5% of IL-10 expressing cells were semimature DCs, and 46.5% of IL-10 expressing semimature DCs in psoriasis skin co-expressed BDCA-3." (PMID 36110854, 2022). "Another important cytokine discussed in relation to psoriasis and neurodegeneration is IL-10, which was investigated in the curcumin model (described more thoroughly below)." (PMID 36226313, 2022). "In a separate study, BLIMP-1 (B lymphocyte-induced maturation protein-1) and IL-10 expression within T-cells were found to be increased in resolved psoriasis skin after IL-23 blockade." (PMID 36110854, 2022). "Sensing of TNFα and IL22 serum levels using the corresponding receptors and linking their downstream signaling in an AND-gate logic enabled the expression of the anti-inflammatory cytokines IL4 and IL10 to treat psoriasis or prevent its development." (PMID 36225597, 2022). "For instance, in psoriasis, low levels of IL-10 have been reported in comparison to other inflammatory skin conditions, while contrarily, enhanced expression of IL-23/IL-17 pathway cytokines has been widely confirmed in psoriatic lesions." (PMID 34616394, 2021). "The administration of IL-10, for example, has already shown promising results in the treatment of RA and psoriasis." (PMID 33679743, 2021). "Polarized by Th2 cytokines (e.g., IL-4), M2 macrophages involved in anti-inflammation and repair process in psoriasis by secretion anti-inflammation cytokines (e.g., IL-10, Arg-1)." (PMID 33858431, 2021). "This is also supported by immunohistochemical results suggesting a low cutaneous IL-10 protein expression in psoriasis." (PMID 34945130, 2021). "In the animal model used in this study, the serum in IMQ-treated mouse showed an elevated level of M1-related cytokines (TNF-α, IL-6, IL-23) along with the decrease of the serum IL-10 level, which was accorded with human psoriasis." (PMID 33858431, 2021). "On the other hand, biological agents targeting TNF, IL-23 and IL-17 have shown promising efficacy during the clinical treatment of psoriasis, while IL-6 inhibitors, IL-21 inhibitors and recombinant human IL-10 treatment didn’t attain the results as expected." (PMID 34975883, 2021). "Topical application of sodium butyrate to imiquimod-induced psoriasis-like dermatitis in mice increased IL-10 and Foxp3 transcripts and reduced inflammation and IL-17A transcripts." (PMID 34501328, 2021). "This suggests that upregulation of IL-10 is involved in the spontaneous improvement of psoriasis symptoms after 5 to 6 days in murine IMQ model and probably explains the spontaneous improvement observed in the IMQ mouse model." (PMID 34616394, 2021). "IL-10, IL-17A, IL-17RA (interleukin 17A receptor), IL-23A (interleukin 23 subunit α) and IL-23R (interleukin 23 receptor) in the development of psoriasis." (PMID 34945130, 2021). "In psoriasis, recombinant human IL-10 treatment has been demonstrated to improve psoriatic symptoms in clinical trials." (PMID 34616394, 2021).
psoriasis (continued). "The present study examines the expression of the genes IL-10, IL-17A, IL-17RA, IL-23A and IL-23R in the skin and peripheral blood of patients with psoriasis and of healthy people, to identify potential factors regulating the development of psoriatic lesions." (PMID 34945130, 2021). "It is possible that suppression of IL-23-mediated psoriasis-like inflammation by Bregs was mainly IL-10-dependent." (PMID 33483537, 2021). "Taken together, our data indicate that in the IMQ-induced psoriasis mouse model, IL-10 neutralization enhances skin thickness through facilitating keratinocyte proliferation." (PMID 34616394, 2021). "This indicates that IL-19 and IL-24, rather than IL-22, IL-17A or IL-17F, were responsible for the late stage (day 10) keratinocyte hyper-proliferation and acanthosis in the IMQ-induced psoriasis mouse model during anti-IL-10 treatment." (PMID 34616394, 2021). "We found lower IL-10 mRNA levels in PBMCs of psoriasis patients when compared to healthy controls, especially in psoriatic BS syndrome patients, in disagreement with the elevated fraction of CD14+HLA-DR−/low MDSC/ CD14+ cells." (PMID 32382290, 2020). "Compared with healthy controls, the mRNA expression of Arg-1, TNF-α, ROR-γ, and PD-L1 was increased, while the mRNA expression of PD-1 and IL-10 was decreased in PBMCs from psoriasis patients." (PMID 32382290, 2020). "A previous study had found that Mo-MDSCs from psoriasis patients have decreased PD-1 and IL-10 expressions, while the PD-L1 expression in psoriatic MDSCs was not significantly changed when compared to healthy control Mo-MDSCs." (PMID 32382290, 2020). "A similar finding has been recently described in a psoriasis murine model where the administration of anti- IL-17A or IL-23p19 induced a significant increase in the number or Foxp3+ IL-10+ Treg cells." (PMID 32630692, 2020). "Taken together, our results suggest that TLR2 signaling directly enhances Treg proliferation and IL-10 production by Tregs and DCs, suppressing imiquimod-induced psoriasis-like skin inflammation." (PMID 33202847, 2020). "mRNA expression of Arg-1, TNF-α, PD-L1, and ROR-γ was increased, while the expression of PD-1 and IL-10 was decreased in the PBMCs of psoriasis patients." (PMID 32382290, 2020). "Plasma concentration of IL-10 in psoriasis patients with normal secretion (↓24.49%, p ≤ 0.0001) and hyposalivation (↓18.37%, p = 0.0001) was significantly lower than in the control group." (PMID 32164227, 2020). "Thus, during the clinical course of imiquimod-induced psoriasis-like skin inflammation, the amplification of Th17 responses caused by the up-regulation of IL-23 expression, the impairment in type I interferon and inflammatory cytokines and the decrease in IL-10 expression occurred in IRF5 KO mice." (PMID 32456211, 2020). "We found that the mRNA expression of Arg-1, TNF-α, ROR-γ, and PD-L1 was increased, while that of PD-1 and IL-10 mRNA was decreased in the PBMCs of psoriasis patients group." (PMID 32382290, 2020). "Statistical analysis of qRT-PCR results indicated that the mRNA expression of Arg-1, TNF-α, PD-1, PD-L1, ROR-γ, and IL-10 in the PBMCs of psoriasis patient group was significantly different from expression levels of the control group." (PMID 32382290, 2020). "As expected, Th17-cell infiltration was decreased in psoriasis patients while anti-inflammatory IL-10 expression from Th1-cells was increased following the administration of IL-23 inhibitors." (PMID 31295952, 2019). "As already reported by other studies, the levels of anti-inflammatory molecules like IL-10 and IL-11 reduce in some inflammatory conditions like infection and psoriasis." (PMID 31878248, 2019). "In this meta‐analysis, we systematically reviewed case–control studies on the association between psoriasis risk and genetic variants in the IL1‐RN and IL‐10 genes." (PMID 30523673, 2019).
psoriasis (continued). "Treatment with recombinant IL‐10 has been shown to be effective in reducing the inflammatory reactions and disease severity in psoriasis patients." (PMID 30523673, 2019). "Studies performed in patients with psoriasis showed that the levels of IL-10 are decreased in the patients’ serum." (PMID 30744173, 2019). "The advanced stages of HCC displayed also high levels IL-10, in contrast with psoriasis where IL-10 is usually low." (PMID 29546055, 2018). "Our preliminary data showed that Apremilast, a phosphodiesterase-4(PDE-4) inhibitor, used in the treatment of PsA and psoriasis (Ps) increased IL-10-producing Bregs and reduced IFNγ+CD3+ T cells and IL-17+CD3+ T cells." (PMID 32185301, 2018). "Supplementation of recombinant human IL-10 in psoriasis patients provided some clinical improvement, whereas it failed to improve Crohn’s disease or rheumatoid arthritis." (PMID 29765083, 2018). "For example, regulatory B cells especially those producing IL-10 can suppress psoriasis-like skin inflammation in imiquimod-induced model." (PMID 30038329, 2018). "To support the beneficial effects of glycolipids on skin inflammation, we analyzed the production of several pro-inflammatory cytokines that are highly involved in psoriasis as well as the anti-inflammatory cytokine IL-10." (PMID 29295585, 2017). "In this sense, IL-10 is a rapid-response cytokine that ameliorates the acute immune response that occurs in recurrent diseases such as psoriasis or IBD." (PMID 29295585, 2017). "TNF-α (pro-inflammatory) and IL10 (anti-inflammatory) are important cytokines in the pathogenesis of chronic inflammatory immune-mediated diseases such as psoriasis and IBD." (PMID 28486503, 2017). "Initial causative research has identified strong association between psoriasis and the interleukin genes (IL4, IL10, IL12B, IL13, and IL23R) in the northern European from US and UK." (PMID 24971308, 2014). "We genotyped seven single-nucleotide polymorphisms (SNPs) in candidate genes of six ILs: IL4, IL10, IL12B, IL13, IL15, and IL23R, which have been shown in the literature to be associated with psoriasis in other ethnic groups." (PMID 24971308, 2014). "We therefore examined the expression of these regulatory mediators in LCs isolated from DKO* mice and found that LCs from mice with psoriasis-like skin inflammation produced substantially higher levels of IL-10 than those derived from jun/junBf/f mice." (PMID 25216727, 2014). "In an Egyptian population (46 cases and 96 controls), an association was established between psoriasis and SNPs in IL6 (CC genotype in rs1800795) and IL10 (GG genotype in rs1800896)." (PMID 24069534, 2013). "Systemic administration of recombinant IL-10 has been trialed in patients with psoriasis and Crohn’s disease and for the alleviation of post-operative inflammation." (PMID 23755052, 2013). "A further study on psoriasis patients undergoing IL-10 therapy confirmed induction of systemic neopterin by IL-10 and demonstrated enhanced ex vivo NK cell-derived IFNγ production by cells obtained from cytokine-treated patients." (PMID 23382730, 2013). "There are several polymorphisms associated with risk of psoriasis, including signal transducer and activator of transcription 4 (STAT4), TaqI polymorphisms in vitamin D receptor (VDR) gene, interleukin-10 (IL-10) polymorphisms and LCE3B genes." (PMID 24324571, 2013). "In this first clinical studies the data leads to the suggestion that IL-10 application is rather adequate to prevent than to cure psoriasis." (PMID 22855687, 2012). "In order to explore the relationship between PGGT1B deficiency and inflammation in psoriasis, we measured the mRNA and cytokine expressions of inflammatory factors IL-1β, IL-6, TNF-α, IL-17A, and IL-10 in the most serious stage of skin injury in mice using Luminex and qRT-PCR." (PMID 40430037, 2025).
psoriasis (continued). "Although IL-10 levels were elevated, they may still be insufficient to counteract the pro-inflammatory environment characteristic of psoriasis, underscoring the limited effectiveness of IL-10′s immunoregulatory function in this context." (PMID 40076417, 2025). "In this study, in order to explore the relationship between PGGT1B deficiency and inflammation in psoriasis, we also detected the mRNA and cytokine expressions of inflammatory factors IL-1β, IL-6, TNF-α, IL-17A, and IL-10 in the most serious stage of skin injury in mice." (PMID 40430037, 2025). "Serum levels of IL-10 and TGF-β were measured alongside the analysis of FOXP3 variants due to their close association with FOXP3 and their significant roles in the pathogenesis of psoriasis." (PMID 40076417, 2025). "Authors of the study speculate that increased numbers of IL-10 in psoriatic nails might represent some significant differences in the pathogenesis of psoriasis at the cutaneous and nail levels." (PMID 39598023, 2024). "Additionally, IL-10 decreases the beginning of psoriasis by regulating regulatory B cells, which is another way in which it performs its anti-inflammatory role." (PMID 39026678, 2024). "Others suggest that they may exert an anti-inflammatory role in psoriasis by increasing the production of IL-10 (or IL-23 in case of LC depletion)." (PMID 38793117, 2024). "Skin sections from IMQ-treated IL-10−/− mice showed histological characteristics of psoriasis, including increased epidermal thickness, acanthosis, and parakeratosis in the stratum corneum, all of which were much more prominent than those observed in the skin sections of IMQ-treated DKO mice." (PMID 37717073, 2023). "The increased IL-17/IL-10 ratio further confirms the imbalance of Th17/Treg cells in psoriasis." (PMID 37596509, 2023). "In a recently published article, the authors indicate that oestrogen has a dual potential in the pathogenesis of psoriasis, including suppression of inflammation by enhancing IL-10 production and the enhancement of inflammation by induction of IL-22 and IL-23 expression." (PMID 38139164, 2023). "Early phase I and II studies showed a trend toward favorable responses of systemically administered IL-10 in psoriasis and Crohn’s disease patients, but larger studies revealed only a slight clinical benefit, due to the double anti- and pro-inflammatory properties of this cytokine." (PMID 37359549, 2023). "The role of other cytokines in psoriasis is often controversial, including IL-4, IL-10, and IL-13." (PMID 36618400, 2022). "The use of anti-IL10 antibodies was also assayed in other inflammatory diseases, including psoriasis lesions; anti-IL10 antibody treatment upregulates IL-17A, which plays a central role in psoriasis pathogenesis." (PMID 36297479, 2022). "Notably, clinical trials of IL-10 administration for psoriasis treatment have shown limited success, but it yields some promising results." (PMID 35869084, 2022). "Previously, our group has demonstrated that apremilast, a phosphodiesterase 4 inhibitor successfully used for the treatment of the disorder, increases IL-10 producing regulatory B cells and decreases IFNγ and IL-17 producing pro inflammatory T subsets in psoriasis and psoriatic arthritis patients." (PMID 35925616, 2022). "Moreover, sensors can cure psoriasis through sensing TNF-a and IL-22 as biomarkers of psoriasis with the following expression of the therapeutic cytokines IL-4 and IL-10." (PMID 34829757, 2021). "This suggests that IL-10 may have anti-psoriatic effects and could be an alternative form of therapy for psoriasis." (PMID 34945130, 2021). "It is possible therefore that IL-10 might have a certain role in the regression of psoriasis and may be considered as a therapeutic approach; however, further investigations are needed to establish its exact anti-psoriatic role." (PMID 34945130, 2021).